IL1B (interleukin 1 beta)
Diseases named in the same sentence as IL1B in open-access papers (continued):
Sharing a sentence is not in itself a finding about the gene and the disease.
epilepsy (265 papers, 2009 to 2026). A brain disorder characterized by episodes of abnormally increased neuronal discharge resulting in transient episodes of sensory or motor neurological dysfunction, or psychic dysfunction. "The study findings indicate a noteworthy association between serum IL‐1β levels and medication resistance in pediatric patients diagnosed with epilepsy." (PMID 40103702, 2025). "Further, epilepsy associated neuroinflammation is characterized by elevated levels of IL-1β, and the same been implicated in both seizure activity and cognitive decline." (PMID 40291844, 2025). "The PI3K/AKT signaling pathway, critical for cellular survival and inflammation, has been implicated in epilepsy, with interleukin‐1β (IL‐1β) playing a central role." (PMID 40542608, 2025). "Apart from that, we saw that several cytokine profiles were correlated with post-TBI symptoms, as IL-8 was linked to post-TBI fatigue and IL-1β to post-TBI epilepsy and the need for pharmacological treatment." (PMID 41517435, 2025). "IL-1β interacts with its specific receptor IL-1R1, implicated in neuroinflammation response in epilepsy pathogenesis." (PMID 38087170, 2024). "Injection of lipopolysaccharide-induced inflammation in rats decreased the seizure threshold and increased susceptibility to epilepsy, resulting in increased cytokine levels (IL-1β or TNFα) in the brains of epileptic rats." (PMID 36518035, 2023). "It has been reported that in anti-NMDAR encephalitis, microglia can be recruited by the Toll-like receptor (TLR) system, polarize to M1 type, release IL-1β, further cause neuroinflammation, and thus lead to epilepsy." (PMID 36389787, 2022). "In conclusion, when our study results and the literature are evaluated together, although long-term use of fingolimod showed the anti-inflammatory effect in epilepsy more prominently, it caused a decrease in serum IL-1β even in acute application." (PMID 36580959, 2022). "In vivo studies also proved that activated glial cells produce large amounts of proinflammatory cytokines such as TNF-α, IL-1β, and IL-6, which, in turn, cause neuronal damage in the hippocampus of rats with epilepsy." (PMID 35456948, 2022). "Inflammatory cytokines, including interleukin-1β(IL-1β), have been reported to be associated with epilepsy." (PMID 35054141, 2022). "In a meta-analysis, an association was found between the risk of febrile seizures and epilepsy and polymorphism in the IL-1β gene." (PMID 36061386, 2022). "In animal models of epilepsy, the activation of IL-1β-related pathways was associated with neurodegeneration and BBB breakdown." (PMID 35326336, 2022). "In COVID-19 patients, an increase in the production of pro-inflammatory cytokines (TNF-α, IL-6, IL-1B) had been reported, which is linked to neurotoxicity and epilepsy." (PMID 34209535, 2021). "CARD8 and IL1B polymorphisms were previously associated with MRI brain injury patterns, that were important predictors of epilepsy and CP in our study." (PMID 34573127, 2021). "CARD8 rs2043211 was associated with lower epilepsy risk, while IL1B rs16944 was associated with higher epilepsy risk, (when stratified for IL1B rs16944 or CARD8 rs2043211 genotype, respectively)." (PMID 34573127, 2021). "The expression of IL-1β increases epilepsy susceptibility and neuronal excitability by directly inhibiting GABAA receptor and promoting the phosphorylation of NR2B subunit of NMDA receptor." (PMID 34976232, 2021). "After adjustment for neonatal convulsions, we observed a nominally significant interaction between CARD8 rs2043211 and IL1B rs16944 and epilepsy risk (p = 0.033)." (PMID 34573127, 2021). "Similar, although not significant trend was observed for the interaction between CARD8 rs2043211 and IL1B rs1143623 and epilepsy risk (p = 0.051)." (PMID 34573127, 2021).
epilepsy (continued). "These series of pericyte-related modifications are promoted by proinflammatory cytokines, of which the most pronounced alterations are caused by IL-1β, a cytokine involved in the pathogenesis of epilepsy." (PMID 34209145, 2021). "Carriers of at least one polymorphic CARD8 rs2043211 allele were less likely to develop epilepsy only in carriers of two normal IL1B rs16944 alleles (ORadj = 0.03 95% CI = 0.00–0.55; padj = 0.019)." (PMID 34573127, 2021). "In our study, carriers of at least one polymorphic CARD8 rs2043211 allele were less likely to develop epilepsy only in carriers of two normal IL1B rs16944 or rs1143623 alleles." (PMID 34573127, 2021). "The interaction between CARD8 rs2043211 and IL1B rs16944 was associated with epilepsy after HIE: CARD8 rs2043211 was associated with lower epilepsy risk, but only in carriers of two normal IL1B rs16944 alleles (ORadj = 0.03 95% CI = 0.00–0.55; padj = 0.019)." (PMID 34573127, 2021). "Carriers of at least one polymorphic CARD8 rs2043211 allele were less likely to develop epilepsy only in carriers of two normal IL1B rs1143623 alleles (ORadj = 0.05 95% CI = 0.00–0.69; padj = 0.025)." (PMID 34573127, 2021). "Correlation analysis showed that serum levels of IL-1β were significantly associated with disease severity in children with epilepsy." (PMID 34976232, 2021). "The most important finding was that the interaction between CARD8 rs2043211 and IL1B rs16944 was associated with epilepsy after HIE." (PMID 34573127, 2021). "The expression of IL-1β genes is enhanced in patients with epilepsy, and its increase is associated with the severity of seizures in animal models of epilepsy." (PMID 33113868, 2020). "The novel finding of the study is the influence of Ala16Val MnSOD gene polymorphism-VV genotype on inflammatory (IL-6, IL-1β), apoptotic (caspases -1 and -3) and antioxidant enzyme (MnSOD) in epilepsy." (PMID 32219137, 2020). "Elevated levels of IL-1β were found in serum and in CSF in subjects with increased risk of developing epilepsy following brain injury." (PMID 31156384, 2019). "Experimental research associated the IL-1β production in epileptogenic brain areas with acute and subsequently, chronic neuroinflammation in epilepsy." (PMID 31208341, 2019). "An equally potent inflammatory cytokine IL1B was also found to be associated with epilepsy when a polymorphism in that gene responsible for increasing the production of IL-1β was detected in patients with temporal lobe epilepsy (TLE)." (PMID 31666079, 2019). "Continuous activation of the IL-1β system causes epilepsy and inflammation, which form a positive feedback loop whereby seizures cause inflammation and inflammation leads to nerve cell excitability and seizures." (PMID 30514296, 2018). "IL-1β is a potent pro-inflammatory cytokine, which is implicated in various neurological disease states from neuronal hyperexcitability in epilepsy, to impairments in learning and memory, as well as perpetuation of sickness and depressive behaviors." (PMID 29403490, 2018). "A recent study of patients with moderate to severe cerebral trauma found a relationship between cerebrospinal fluid IL1-β levels and an allelic variant of the IL1-β gene to the risk of developing epilepsy." (PMID 28120042, 2017). "A meta-analysis further showed that two alleles of proinflammatory cytokines (IL-1α-889 and IL-1β-511) and the serum concentration of IL-6 were significantly associated with epilepsy." (PMID 27882059, 2016). "The most pronounced epilepsy-associated differences were decreased levels of eotaxin, IL-1β, C-reactive protein, and vascular cell adhesion molecule (VCAM)-1 and increased IL-12 p70 levels." (PMID 27737716, 2016). "Higher CSF/serum IL-1β ratios were correlated with an increasing risk for diverse types of epilepsy." (PMID 27882059, 2016).
epilepsy (continued). "Taken together, these findings indicate that alterations in expression of Kir4.1 occurring in epilepsy-associated lesions are possibly influenced by the local inflammatory environment and in particular by the inflammatory cytokine IL-1β." (PMID 23270518, 2012). "Given that excessive production of TNF‐α, IL‐6, and IL‐1β has been implicated in neurodegenerative diseases and epilepsy, our findings suggest that Listerin may serve as a protective factor against pathological neuroinflammation." (PMID 40448625, 2025). "We have also demonstrated that neuroinflammation was induced in febrile seizures, and the increased pro‐inflammatory factors, such as interleukin 1β (IL‐1β) and IL‐6, might be responsible for the epileptogenesis in fever‐associated epilepsy." (PMID 38357846, 2024). "Furthermore, studies involving IL1B polymorphisms in humans have shown an association between a variant located at the promoter region of IL1B (C-511T), which produces less protein, and increased risk for epilepsy and febrile seizure." (PMID 35061107, 2023). "Summary of studies on the HMGB1/TLR4 and IL-1β/ IL-1R pathways and their association with epilepsy." (PMID 35837232, 2022). "Exacerbated inflammation could be a consequence as well as a cause of epilepsy, and several inflammatory mediators, such as IL1β, TNF, and IL6, have been detected in surgically resected brain tissue from epileptic patients." (PMID 33407600, 2021). "Similarly, carriers of at least one polymorphic IL1B rs16944 allele were more likely to develop epilepsy only in carriers of at least one polymorphic CARD8 rs2043211 (ORadj = 13.33 95% CI = 1.07–166.37; padj = 0.044)." (PMID 34573127, 2021). "We therefore examined the interactions between CARD8 and IL1B polymorphisms and epilepsy or CP." (PMID 34573127, 2021). "Furthermore, TNF-α and IL-1β are found to be increased in the kainic acid-induced epilepsy model, and seizure susceptibility correlates with microglia development in the hippocampus." (PMID 34948222, 2021). "Elevated levels of IL-1β in CSF/serum/brain tissue are associated with the development of epilepsy." (PMID 34122298, 2021). "Additionally, IL1B rs16944 was associated with higher epilepsy risk only in carriers of at least one polymorphic CARD8 rs2043211 (ORadj = 13.33 95% CI = 1.07–166.37; padj = 0.044)." (PMID 34573127, 2021). "Moreover, the expression of other pro‐inflammatory genes associated with epilepsy, such as IL1B and CCL2, was decreased by miR‐132 overexpression in astrocytes." (PMID 31408236, 2020). "In consideration that changed IL-1β levels could directly affect seizure susceptibility, whether the involvement of IL-1β in epilepsy-induced sleep disruption is caused by its direct effect on seizures needs further investigation." (PMID 32793110, 2020). "Moreover, increased serum and cerebral spinal fluid (CSF) levels of IL-1β have been associated with an increased risk of subsequent epilepsy after moderate-to-severe brain injury." (PMID 31156384, 2019). "Based on the origin of metabolites in the CSF, an association between the occurrence of IL-1β in CSF and the brain tissue would have been highly plausible and could tell more about the role of IL-1β in epilepsy." (PMID 31208341, 2019). "However, to better understand the pathogenic role of this cytokine in epilepsy, further evaluation of IL-1β in brain tissue is desired." (PMID 31208341, 2019). "Furthermore, the patients with C to T genotype rs1143634 showed lower serum IL-1β levels and higher IL-1β CSF/serum ratios, seemingly associated with both, seizure frequency and the probability of developing subsequent epilepsy." (PMID 31156384, 2019). "IL-1β has also been linked to other epilepsies in addition to PTE." (PMID 28086980, 2017). "Interestingly, miR-146a are upregulated commonly associated with IL-1β in epilepsy." (PMID 35898503, 2022).
epilepsy (continued). "In the clinic, in a small cohort study of patients with neonatal HI, elevated IL-6, TNFα, and IL-1β were found to be associated with the subsequent onset of epilepsy, suggesting that these cytokines may hold value as predictive biomarkers of later life epilepsy risk." (PMID 32116690, 2020). "Across both cohorts, neonates with epilepsy had higher concentrations of the pro-inflammatory cytokine IL-1β and the neuronal injury marker UCHL1 compared to those without epilepsy." (PMID 42106818, 2026). "These established evidences highlighted the correlation of serum IL-1β with severity and drug resistance in patients with epilepsy, though more investigations considering various etiologies of epilepsy are required." (PMID 41155637, 2025). "Clinical studies have found that the expression levels of IL‐1β,20 IL‐6,21 IL‐18,20, 22 and IL‐33 23 in the serum of epilepsy patients are elevated." (PMID 40103702, 2025). "Excitotoxicity can influence acute seizures and the development of epilepsy; IL-1β potentially worsens this process by promoting glutamate release and modifying synaptic plasticity." (PMID 41328216, 2025). "At present, studies have generally suggested the involvement of IL-1β in epilepsy, and most studies have shown that IL-1β levels in both serum and cerebrospinal fluid are significantly increased in patients with epilepsy." (PMID 39858450, 2025). "Among the pro-inflammatory cytokines, IL-1β contributes significantly to both the onset of epilepsy and the persistence of seizures." (PMID 40558831, 2025). "As an endogenous antagonist of IL-1β signal, IL-1Ra was shown to be elevated in serum or in CSF from patients with epilepsy." (PMID 41155637, 2025). "Brain inflammation in epilepsy is primarily characterized by the proinflammatory mediators in the epileptic focus, such as interleukin‐1β (IL‐1β), high‐mobility group box 1 (HMGB1), and tumor necrosis factor‐α (TNF‐α)." (PMID 40878478, 2025). "This is supported by the involved role of IL-1β in BBB permeability alteration and a significant increase in CSF-serum ratio of IL-1β in patients with epilepsy." (PMID 41155637, 2025). "IL-1β is a key inflammatory mediator that contributes to the pathogenesis of epilepsy, particularly in drug-resistant cases." (PMID 40291844, 2025). "VX-765 (Belnacasan), a caspase-1 inhibitor capable of crossing the blood–brain barrier (BBB), blocks NLRP3-mediated IL-1β and IL-18 activation and has completed Phase II trials for epilepsy with mixed efficacy (NCT01048255)." (PMID 40427569, 2025). "Serum levels of 5 cytokines related to neuroinflammation in epilepsy patients (IL1b, IL4, IL6, IL10, and TNF‐alpha) were measured using SIMOA, an ultrasensitive ELISA technique for analyzing molecules in biological samples." (PMID 40542608, 2025). "Most studies suggested serum IL-1β was significantly elevated in epileptic patients, which indicated serum IL-1β as a biomarker for epilepsy." (PMID 41155637, 2025). "Growing evidence highlights the role of neuroinflammation, particularly the involvement of IL‐1β in the pathogenesis and progression of epilepsy." (PMID 40878478, 2025). "VX-765 is a reversible caspase-1 inhibitor that blocks IL-1β maturation and suppresses IL-1β/IL-1R1 signaling, a pathway critically involved in drug-resistant epilepsy via neuroinflammation and blood–brain barrier disruption." (PMID 41155637, 2025). "Understanding the interplay between NFκB, IL‐1β, and TNF‐α not only sheds light on the mechanisms underlying epilepsy but also opens avenues for identifying potential therapeutic targets." (PMID 41523603, 2025). "Further, a significant decrease in IL-1Ra/IL-1β ratio suggested insufficiency of endogenous inhibitory activity and upregulation of IL-1β signal in epilepsy." (PMID 41155637, 2025). "LEV had direct effects on IL-1β in a previous clinical study of 22 epilepsy patients, which revealed significantly decreased IL-1β levels two hours after LEV administration." (PMID 40806813, 2025).
epilepsy (continued). "The administration of therapeutic levetiracetam doses decreased serum IL-1β level in patients with different types of epilepsies as well as serum IL-1β and TNF-α level in healthy female subjects." (PMID 40431461, 2025). "The expression of IL-1β and its receptor, IL-1R1, is significantly upregulated in postoperative focal brain tissues of epilepsy patients and in various animal models of epilepsy." (PMID 41306289, 2025). "IL-1β can also be detected in extra-brain samples from patients with seizures and epilepsy, such as serum, plasma, cerebrospinal fluid (CSF), especially in serum specimens." (PMID 41155637, 2025). "Among these, TNF‐α, IL‐1β levels and its receptor IL‐1R1 in human serum have been suggested to correlate with the severity of epilepsy." (PMID 39907034, 2025). "The functional role of miRNAs produced by astrocytes in response to IL-1β-induced inflammation was also investigated in epilepsy." (PMID 40558831, 2025). "IL-1β and IL-6 transcript levels were still significantly elevated up to 7 weeks post-SE during the chronic phase of epilepsy." (PMID 41445743, 2025). "Upregulation of IL-1β can be detected in the epileptogenic cortex in various types of epilepsy in patients and animal models." (PMID 41155637, 2025). "In epilepsy pathology, IL-1β not only directly enhances neuronal excitability but also acts on cerebrovascular endothelial cells." (PMID 40641625, 2025). "To this end, we analyzed the transcript levels of the inflammasome mediators Il1β, Il6, Il12, Il10, Tnfα, Cd68, Ccl2, and Ccl5, which are upregulated in pilocarpine‐ and kainic acid‐induced epilepsy models." (PMID 40608247, 2025). "Targeting IL-1β-mediated NF-κB signaling is also a therapeutic choice for epilepsy-related neuroinflammation." (PMID 41155637, 2025). "Studies have shown that the expression of IL-1β is increased in epilepsy, which correlates with a rise in both the frequency and intensity of seizures." (PMID 40291844, 2025). "Elevated levels of IL-1β were reported in epilepsy patients and in experimental models of epilepsy, and the majority of studies suggest that elevated IL-1β levels increase seizure susceptibility and promote epileptogenesis." (PMID 41154178, 2025). "Due to the importance of the IL-1β/IL-1R1/IL-1Ra pathway in epileptogenesis, the IL-1β/IL-1R1/IL-1Ra pathway is considered a potential target for epilepsy treatment." (PMID 41155637, 2025). "Clinically, the serum levels of IL-1β, IL-6, and IL-1Ra are significantly elevated in patients with epilepsy." (PMID 40170730, 2025). "It is the way IL-1β exists in the brain tissue.When the body develops epilepsy due to brain injury,craniocerebral injury, intracranial infection, or otherpathologies, its level is clearly elevated." (PMID 39139150, 2024). "With the activation of astrocytes, the influential pro-inflammatory cytokine IL-1β induces the generation of IL-6 and TNF-α, both of which are strongly linked to epilepsy." (PMID 39598325, 2024). "Among the tested drugs, Andrographolide, known for its antiepileptic activity, exhibited promising interactions with IL1B, suggesting its potential as a therapeutic option for epilepsy." (PMID 38384278, 2024). "Increased pro‐inflammatory cytokines including tumor necrosis factor‐alpha (TNF‐α), IL‐1β, and IL‐6 were also observed in an epilepsy mouse model with Gabrg2+/Q390X knockin, indicating neuroinflammation was one of the mechanisms for genetic epilepsy." (PMID 38357846, 2024). "Compared to the healthy volunteers, epilepsy patients had significantly increased serum levels of the inflammatory factors IL-6, IL-1β, TNF-α, and CRP (P < 0.05), while SIRT3 levels were significantly decreased." (PMID 39091611, 2024). "Elevated levels of IL‐1β, IL‐6, IL‐9, and TNF‐α have been linked to the subsequent onset of epilepsy in children who experienced acute seizures." (PMID 38361811, 2024).